FAM161A (FAM161 centrosomal protein A)
Description:
Involved in ciliogenesis.
Synonyms: FLJ13305; RP28
Tractability: PROTAC: UniProt records ubiquitination sites on it; ubiquitination databases record sites on it.
Gene: Protein-coding gene on chromosome 2 (61,824,848 to 61,854,143, reverse strand). Ensembl gene ENSG00000170264.
Subcellular location: Cytoplasm, cytoskeleton, cilium basal body; Cell projection, cilium; Cytoplasm, cytoskeleton, microtubule organizing center, centrosome, centriole
Subcellular location (Human Protein Atlas): Basal body; Centrosome; Flagellar centriole; Cytosol; Golgi apparatus; Nucleoplasm
Gene Ontology:
Molecular function: identical protein binding; microtubule binding; protein binding
Biological process: cilium assembly; cilium organization
Cellular component: astral microtubule; centriole; centrosome; ciliary basal body; mitotic spindle; mitotic spindle pole; photoreceptor connecting cilium; photoreceptor inner segment; spindle microtubule; cilium; cytoskeleton
Genetic constraint (gnomAD): Loss-of-function variants: 57 observed, 69.37 expected, observed/expected ratio (o/e) 0.82, 90% interval 0.66 to 1.02. The upper end of that interval is the gene's LOEUF score, 1.02, which puts it in group 4 of 6, group 1 being the genes least tolerant of losing a copy. Missense variants: 858 observed, 860.35 expected, observed/expected ratio (o/e) 1, 90% interval 0.94 to 1.05. Synonymous variants: 291 observed, 306.11 expected, observed/expected ratio (o/e) 0.95, 90% interval 0.86 to 1.05.
Homologues: Orthologues: chimpanzee FAM161A (99% identical), macaque FAM161A (95% identical), pig FAM161A (78% identical), dog FAM161A (67% identical), guinea pig FAM161A (67% identical), rat Fam161a (50% identical), tropical clawed frog fam161a (39% identical), mouse Fam161a (37% identical), zebrafish fam161a (33% identical). Paralogues in human: FAM161B (23% identical), TSGA10IP (13% identical).
Diseases named in the same sentence as FAM161A in open-access papers:
FAM161A is named in the same sentence as 31 diseases in open-access papers, as found by Europe PMC text mining. Sharing a sentence is not in itself a finding about the gene and the disease. The quoted sentences say what the papers report.
retinitis pigmentosa (16 papers, 2009 to 2025). Retinitis pigmentosa (RP) is an inherited retinal dystrophy leading to progressive loss of the photoreceptors and retinal pigment epithelium and resulting in blindness usually after several decades. "Mutations of FAM161A, an inner scaffold component associated with retinitis pigmentosa, result in microtubule doublet disorganization, outer segment collapse and ultimately photoreceptor degeneration." (PMID 41147396, 2025). "Retinitis pigmentosa-28 (RP28) is a recessive retinal disorder leading to blindness associated with FAM161A gene defects." (PMID 38504136, 2024). "FAM161A is a ciliary protein which is expressed in photoreceptors, and pathogenic variants in this gene cause retinitis pigmentosa (RP)." (PMID 35408898, 2022). "Family-based studies and homozygosity mapping have linked coding mutations in the gene FAM161A to a hereditary form of Retinitis Pigmentosa (RP), a retinal ciliopathy leading to progressive degeneration of photoreceptors." (PMID 30886144, 2019). "Mutations in FAM161A are reported to be associated with early onset recessive retinitis pigmentosa while mutations in ALMS1 are associated with Alstrom syndrome and non-syndromic Leber’s congenital amaurosis." (PMID 26352687, 2015). "Retinitis pigmentosa-type 28 (RP28) is the consequence of bi-allelic null mutations in the FAM161A gene, which codes for a protein (FAM161A) known to form part of the inner scaffold structure maintaining microtubule doublets of the connecting cilium and the basal body/centriole." (PMID 38504136, 2024). "Pathogenic variants in FAM161A are the most common cause of retinitis pigmentosa in Israel." (PMID 36420180, 2023). "Given that CCP5 deficiency is linked to retinitis pigmentosa, and that we recently showed that FAM161A-associated retinitis pigmentosa RP28 is due to structural defects at the level of the CC, we investigated whether this structural element was affected in deglutamylase mutants." (PMID 39528655, 2024). "For example, we recently used ExM to fine-tune the re-expression of Fam161a in a mouse model of retinitis pigmentosa." (PMID 41147396, 2025). "Furthermore, we show that Fam161a disruption in mouse leads to specific CC inner scaffold loss and triggers microtubule doublet spreading, prior to outer segment collapse and photoreceptor degeneration, suggesting a molecular mechanism for a subtype of retinitis pigmentosa." (PMID 35709082, 2022).
retinal degeneration (13 papers, 2014 to 2025). Degeneration of the retina. "Recently, Beryozkin and his colleagues have successfully generated a knockout mice model for Fam161a deficiency; Fam161a knockout mice display retinal degeneration phenotype as well as enhanced molecular generative markers such as microglia." (PMID 36840007, 2023). "The FAM161A gene has been implicated in retinal degeneration in humans and progressive retinal atrophy in dogs." (PMID 30022108, 2018). "Two transgenic mouse lines mimicking retinal degeneration associated with ciliopathy of the photoreceptors, such as the Fam161atm1b/tm1b (Fam161a knockout) mouse and the Bardet Biedl Syndrom-10 (BBS10 KO mice), also presented isolated photoreceptors with high H3K27me3 level." (PMID 34502238, 2021). "FAM161A mutations are the most common cause of inherited retinal degenerations in Israel." (PMID 33479377, 2021). "The present work focused exclusively on the gene therapy effect of FAM161A expression on cilium structure reorganization, because it is the obvious link of cilium structure defect with retinal degeneration." (PMID 38504136, 2024). "Mutations in the proteins that interact with FAM161A result in diverse phenotypes, some of which present similarly to FAM161A mutations; for example, mutations in POC1B, Centrin 2 and Centrin 3 cause retina degeneration." (PMID 39255847, 2024). "Microglia have been previously shown to be activated during retinal degeneration in different retinal degenerative processes, including in the Fam161a gene trap model." (PMID 33479377, 2021). "In this study we report the generation and characterization of Fam161atm1b/tm1b—a KO mouse model for Fam161a, which exhibits retinal degeneration with autosomal recessive inheritance." (PMID 33479377, 2021). "We identified a total of nine causal mutations, including six novel variants in RPE65, LCA5, USH2A, CNGB1, FAM161A, CERKL and GUCY2D as the underlying cause of inherited retinal degenerations in 13 of 26 pedigrees." (PMID 26352687, 2015). "There are, however, inherited diseases that have been reported to be caused by SINE insertions, including an intronic SINE in FAM161A that is associated with PRA in Tibetan Terriers and Tibetan Spaniels and an exonic SINE in STK38L that causes early retinal degeneration in Norwegian Eklhounds." (PMID 39062732, 2024). "Consistent with the phenotype observed in the cohort of patients analyzed in this study, the RPE65, LCA5, USH2A, CNGB1, FAM161A, CERKL and GUCY2D genes consisting mutations in 13 of the 26 pedigrees have been implicated in causing recessive non-syndromic retinal degeneration." (PMID 26352687, 2015). "FAM161A has been shown to interact with the CRX (Cone-rod homeobox-containing) transcription factor and Lebercilin, both of which have also been implicated in retinal degeneration in humans." (PMID 24705771, 2014).
autosomal recessive retinitis pigmentosa (4 papers, 2014 to 2022). Autosomal recessive retinitis pigmentosa (RP) is an autosomally recessive inherited retinal dystrophy leading to progressive loss of the photoreceptors and retinal pigment epithelium and resulting in blindness usually after several decades. "Mutations in Fam161a are the most common cause of autosomal recessive retinitis pigmentosa in the Israeli-Jewish population, implying the vital roles of this protein in RP pathologies." (PMID 35698136, 2022). "FAM161A mutations are the most common cause of autosomal recessive retinitis pigmentosa in the Israeli-Jewish population." (PMID 32938956, 2020). "FAM161A was previously implicated in autosomal-recessive retinitis pigmentosa and shown to be located at the base of the photoreceptor connecting cilium, where it interacts with several other ciliopathy-associated proteins." (PMID 25018096, 2014). "Mutations in FAM161A were recently reported to cause autosomal recessive retinitis pigmentosa by two independent studies." (PMID 24651477, 2014).
ciliopathy (4 papers, 2014 to 2022). A genetic disorder of the cellular cilia or the cilia anchoring structures, the basal bodies, or of ciliary function. "Because FAM161A was found to be a retinal-ciliopathy-associated protein, the decreased interaction we observed with this retina-specific protein might induce degeneration of rod photoreceptors as a result of POC1B mutations in individuals with CRD." (PMID 25018096, 2014). "Mutations in these ciliary genes are implicated in photoreceptor degeneration related ciliopathies, such as RPGRIP1 in cone dystrophy (CD)/cone-rod dystrophy (CRD), LCA5 and CEP290 in Leber congenital amaurosis (LCA), Fam161A and OFD1 in RP." (PMID 27196396, 2016).
retinal disease (4 papers, 2014 to 2024). "Mutations in FAM161A are linked to certain hereditary retinal diseases, which typically result in progressive vision loss, significantly diminishing survival abilities in the wild." (PMID 39595990, 2024). "RP28 is a recessive retinal disease leading to blindness associated with defects in the FAM161A gene." (PMID 39451224, 2024). "The works of Mercey and colleagues (2022) have proposed a compelling theory to explain FAM161A’s role in retinal disease." (PMID 39062732, 2024). "As the discovery of FAM161A involvement in retinal disease was relatively recent, little is known about the protein's structure and function of the protein in visual pathways." (PMID 24705771, 2014).
myopia (3 papers, 2020 to 2025). "Clinical features that may further support FAM161A as the causative gene include moderate-high myopia, constricted VFs at early ages but with relatively well preserved VA, and paucity of BSP-like pigmentary changes." (PMID 32938956, 2020).
retinal ciliopathy (3 papers, 2014 to 2025). "Interestingly, mutations in FAM161A lead to another retinal ciliopathy, autosomal-recessive RP (RP28).27,28 Binding of FAM161A was validated with coimmunoprecipitation and colocalization studies." (PMID 25018096, 2014).
Blindness (2 papers, 2014 to 2024). Blindness is the condition of lacking visual perception defined as a profound reduction in visual perception. "Recent investigations have revealed that defects in FAM161A represent a rather prevalent cause of hereditary blindness in Israel and the Palestinian territories, whereas they seem to be rarely present within patients from Germany." (PMID 24651477, 2014).
retinal dystrophies (2 papers, 2024). "A gene therapy treatment with the vector combination in the peri-macular region is thus an attractive strategy to change the disease course of retinal dystrophies associated with FAM161A deficiency." (PMID 38504136, 2024).
Mendelian diseases (1 paper, 2018). "The six genes (SCARF2, RD3, COL9A3, FAM161A, RASGRP1 and DLX6) in common between novel contigs, human Mendelian diseases, and hereditary diseases in dogs are significant in known disease phenotypes in humans and animal models." (PMID 30022108, 2018).
FAM161A also shares sentences with these, for which no sentence is quoted: cone and rod dystrophy (3 papers); Leber congenital amaurosis (3); Alstrom syndrome (1); Alzheimer disease (1); amyotrophic lateral sclerosis (1); Bardet-Biedl syndrome (1); blood cancer (1); cerebral amyloid angiopathy (1); cone dystrophy (1); fragile X syndrome (1); hearing loss (1); hypotrichosis (1); Immunodeficiency (1); lipodystrophy (1); neurodegenerative disease (1); retinal (1); Retinal atrophy (1); retinopathy (1); SHORT syndrome (1); Stargardt disease (1); Visual impairment (1).